IDH1 (isocitrate dehydrogenase (NADP(+)) 1)
Diseases named in the same sentence as IDH1 in open-access papers (continued):
Sharing a sentence is not in itself a finding about the gene and the disease.
glioma (continued). "We further observed that the association between 5-mC% level and glioma risk was more evident in the tumors with aggressive phenotypes, that is high-grade tumors, glioblastomas, and tumors negative for IDH1 mutation." (PMID 28968983, 2017). "Another interesting finding is that 5-mC% levels were significantly lower in high-grade tumors and glioblastoma and marginally lower in IDH1 mutation–negative tumors than in low-grade tumors, non-glioblastoma gliomas, and IDH1 mutation–positive tumors." (PMID 28968983, 2017). "To gain further insight on how general this biological observation is we extended our studies to an isogenic model using HCT116 (IDH1-WT/IDH1-R132H) colorectal cancer cells and two patient-derived IDH1-R132H expressing glioma stem-like cells, NCH612 and BT-142." (PMID 29057925, 2017). "For glioma without IDH1 mutation, IDH1 can be targeted using siRNA or antagonist to inhibit enzyme activity and further down-regulating ATK-mTOR signaling and cell proliferation and migration." (PMID 28052098, 2017). "IDH1 and IDH2 mutations have been identified in ∼15–20% of AML and glioma patients." (PMID 29290954, 2017). "The high association between IDH1 and XAF1 status was also observed in recurrent gliomas." (PMID 28122345, 2017). "Moreover, the expression of some key factors in gliomas were detected by QPCR, such as IDH1, TERT, EGFR, PTEN, ATRX." (PMID 28199986, 2017). "Risk backpropagation analysis of our model identified IDH1 and IDH2 mutations (ranks 9, 10) as strongly associated with better prognosis, consistent with the role of these mutations as the primary feature in classifying gliomas." (PMID 28916782, 2017). "We have previously shown that mutation of isocitrate dehydrogenase 1 (IDH1), one of the TCA cycle isozymes commonly mutated in lower grade gliomas, is related to the enhancement of PpIX accumulation and fluorescence by exogenous 5-ALA in malignant glioma cells." (PMID 28939850, 2017). "IDH1 mutant glioma cells might be sensitive to mitochondrial stress, because the IDH1 mutation silences the cytoplasmic, Gln-dependent pathway for metabolites and fatty acids." (PMID 27752843, 2017). "The sensitivity of IDH1 mutant tumors to a PLK1 inhibitor plus TMZ combination may have implications beyond glioma treatment." (PMID 28178660, 2017). "Though limited by the number of orthotopic IDH1 mutant models available, these data suggest that the ability to inhibit 2-HG over a sustained period of time may provide a meaningful survival benefit in patients with IDH1 mutant glioma." (PMID 29062039, 2017). "Furthermore, we have chance to analyse 2-HG production of a generated (genetically modified) homozygous IDH1 mutant glioma cell line – U251 MG." (PMID 28578659, 2017). "Subsequently, it has been shown that >75% of low-grade gliomas and 20% of AML have mutations in IDH1 or IDH2, and mutations are also found in other solid tumors such as chondrosarcoma, cholangiocarcinoma, colon, pancreatic and prostate cancer to varying extents." (PMID 28986582, 2017). "In addition, given that IDH1 mutation lead to a better prognosis of glioma patients, we next evaluated the effect of CNG of these genes on the survival of the patients with different IDH1 mutation status." (PMID 29190914, 2017). "The results suggest that disruption of 2-HG production with brain-penetrant inhibitors in IDH1 mutant gliomas may have substantial patient benefit." (PMID 29062039, 2017). "IDH1 mutation is a key molecular marker in WHO grades II and III gliomas." (PMID 29371945, 2017). "Furthermore, it has been recently demonstrated that IDH1 mutant gliomas particularly profit from aggressive tumour resections." (PMID 27300198, 2017).
glioma (continued). "Also, additional mutations in the IDH2 gene, apart from IDH2 R172 (e.g. R140), which in gliomas occur less frequently than those in the IDH1 gene, give the same phenotype." (PMID 28122345, 2017). "As mentioned, IDH1 mutant glioma models are extremely difficult to propagate in vivo." (PMID 29062039, 2017). "Similar to other mutant selective inhibitors, these findings suggest that there may be heterogeneity in the response to IDH1 mutant inhibitors when used clinically in glioma patients." (PMID 29062039, 2017). "Hence, we prospectively analyzed a series of adult glioma patients and compared 7 Tesla SWI-LIV values to the WHO tumour grade, IDH1-R132H mutational status, and type of CE on MRI." (PMID 27300198, 2017). "Patient-derived in vivo models for the preclinical study of IDH1 mutant glioma are scarce." (PMID 29062039, 2017). "This contradicts our finding that miR-148a is upregulated in IDH1 R132H glioma tissues." (PMID 28445981, 2017). "IDH1/1p19q/H3F3A are the representatives introduced into newly revised 2016 WHO glioma guideline." (PMID 28915860, 2017). "Likewise, targets of epigenetic silencing identified in IDH1-mutant gliomas, including glycolytic genes, retinol binding protein 1, and microRNA miR148a, were all associated with reduced cell proliferation and improved survival." (PMID 27852048, 2017). "The feature maps of IDH1 mutant gliomas showed a more uniform distribution." (PMID 28710497, 2017). "Thus, further characterization of additional models, both inhibitor responsive and non-responsive, is needed to understand the potential predictive value of preclinical modeling in IDH1 mutant patient-derived glioma models." (PMID 29062039, 2017). "The detection of IDH1/2 mutations through the measurement of the 2-hydroxyglutarate (2-HG) oncometabolite levels by MRSI, despite a possible spectral overlap with other metabolites, would be remarkable only if referred to the whole glioma group." (PMID 29207673, 2017). "In the BT142 IDH1 mutant glioma line, these data suggest that 2-HG inhibition may lead to changes in cell differentiation." (PMID 29062039, 2017). "The development of the GB10 model enabled us to better understand the heterogeneity in the treatment response that may be observed clinically for IDH1 mutant glioma." (PMID 29062039, 2017). "This may accelerate the application of IDH1 inhibitors in clinical by applying new indications of this drug, to benefit a large number of patients with glioma or AML." (PMID 28498812, 2017). "Moreover, mutant IDH1 glioma tumors that have a longer survival compared to wild-type IDH1 have a reduced neutrophil infiltration." (PMID 29123517, 2017). "New IDH1 mutant glioma models are needed to examine the spectrum of responses to treatment that may be observed clinically following the administration of IDH1 mutant inhibitors." (PMID 29062039, 2017). "Grade II-III gliomas lacking the IDH1 mutation are genetically distinct from IDH1 mutant gliomas and are more similar to primary grade IV glioblastomas." (PMID 28178660, 2017). "In addition, the IDH1.R132H, GNAS.R201C, and EGFR.T790M mutations in Glioma, EGC, and NSCLC were the most significantly different point mutations (p = 0.00021, 0.00027 and 0.0011, respectively)." (PMID 29038591, 2017). "Given the contextual microenvironment in which tumor stem cells may proliferate, we sought to understand the potential therapeutic benefit of treating IDH1 mutant glioma cell lines in vivo." (PMID 29062039, 2017). "LncRNA profiling between gliomas with or without IDH1 mutations show significantly altered gene expressions in astrocytic and oligodendroglial tumors." (PMID 28293170, 2017). "IDH1 R132 activating mutations were found by several sequencing studies to be very common in specific types of adult brain tumors, occurring in >70% of adult grade II and grade III gliomas and >80% of adult secondary glioblastoma multiforme (GBM)." (PMID 28785398, 2017).
glioma (continued). "This study provided the first evidence that a meaningful preclinical survival benefit could be obtained from prolonged intracranial 2-HG inhibition in IDH1 mutant glioma." (PMID 29062039, 2017). "However, it is in line with a study showing that NHE-1, another transporter involved in maintenance of intracellular pH and cell survival in glycolytic tumors, is silenced in 1p/19q co-deleted mutant IDH1 gliomas." (PMID 27144334, 2016). "Thus, IDH1-R132H can be used for the diagnosis between grade II/III gliomas, secondary GBM and primary GBM." (PMID 27713914, 2016). "Mutations in the metabolic enzyme isocitrate dehydrogenase (IDH) characterize the majority of LGGs and a small percentage of GBMs, and define subtypes that associate with better responses to radiation treatment and an improved prognosis compared with gliomas with wild-type (WT) IDH1–4." (PMID 27820599, 2016). "Similar to our HK2 protein results, primary GBM operative samples and GBM cultures had significantly higher hexokinase activity compared to normal controls (11 fold higher, (*p < 0.05)) and 6 fold higher (*p < 0.05) when compared to grade II gliomas (IDH1 mutant oligodendrogliomas) (p < 0.05)." (PMID 27588472, 2016). "However, the size of uncensored patients with IDH1 aberrations (12 gliomas, or 4.4%) prevented us from making statistically significant statements about the difference of median survival time with this additional genetic criterion." (PMID 27898674, 2016). "Additionally, glioma samples with wild-type IDH1 showed higher expression of KIF23 than those with mutant IDH1." (PMID 27013586, 2016). "Recent sequencing of primary and TMZ-treated recurrent gliomas showed the TMZ-driven amplification of mutation heterogeneity (hypermutation phenotype) in IDH1-mutant but not IDH1-wild-type astrocytic gliomas." (PMID 27158244, 2016). "Our finding regarding reduced expression of the MCTs, taken together with reduced intracellular lactate levels and the silencing of LDHA expression, indicate that in mutant IDH1 gliomas in vivo the production of hyperpolarized lactate is likely to be very limited." (PMID 27144334, 2016). "Additionally, some other factors including IDH1 mutation state, KPS, age, and tumor grade, were significantly associated with the overall survival of glioma patients." (PMID 27013586, 2016). "In the present study, for the first time to our knowledge, we illustrated an evaluation formula for the evolution of gliomas by IDH1-R132H combined with ATRX immunohistochemistry and identified the association between IDH1-R132H/ATRX loss and longer progression time interval of gliomas." (PMID 26918938, 2016). "We carried out an unbiased 1H MRS-based metabolomic analysis of glioma cells genetically engineered to express either the wild-type or mutant IDH1 enzyme and found that steady-state levels of glutamate, lactate and PC were reduced in mutant IDH1 cells." (PMID 27144334, 2016). "Discovery of the IDH1 mutation has also led to a molecular (rather than histological) classification of gliomas." (PMID 27014635, 2016). "Our finding that expression of MCTs is reduced in mutant IDH1 gliomas is therefore also unusual." (PMID 27144334, 2016). "Among 196 glial tumors with nuclear ATRX loss, 173 (89 %) had an IDH1 or IDH2 mutation." (PMID 27311324, 2016). "Those 6 significant metabolites separated IDH1 mutation positive from negative glioma patients with 94.4% accuracy." (PMID 26967252, 2016). "However, in the current study, we show that expression of MCT1 and MCT4 is significantly reduced in mutant IDH1 gliomas." (PMID 27144334, 2016). "One study demonstrated that glioma cells harboring mutant IDH1 may maintain cell proliferation via the glutamate metabolism pathway." (PMID 27245697, 2016). "Indeed, the presence of IDH1 mutation was associated with favorable progression-free and overall survival in WHO grade II gliomas who received radio- or chemotherapy." (PMID 26858939, 2016).
glioma (continued). "Two of three grade III gliomas who were examined the sequence of the IDH1 gene revealed IDH1 mutations and one of three did not reveal the IDH1 mutation." (PMID 27456199, 2016). "Our study revealed an intrinsic distinction between IDH1 and IDH2 mutant gliomas, and these mutations should be considered separately because their differences could have implications for the diagnosis and treatment of IDH1/2 mutant gliomas." (PMID 27245697, 2016). "In our 1H-MRS study, we observed a reduction in intracellular lactate levels in IDH1 mutant glioma cells, suggesting that their metabolic reprograming could differ from other types of cancer cells." (PMID 27014635, 2016). "Strikingly, mutations in IDH1 and IDH2 are mutually exclusive in gliomas." (PMID 27245697, 2016). "Given that the cytosolic pathway has been shown to be important in hypoxic reductive carboxylation for lipogenesis, and that gliomas appear to ‘favor’ IDH1 mutations, there may be a requirement for IDH2 wild‐type activity in hypoxic IDH1 mutant gliomas." (PMID 27196610, 2016). "Our laboratory has used MRS to investigate the metabolic reprogramming of mutant IDH1 glioma cells." (PMID 27144334, 2016). "We used immunohistochemistry (IHC) to detect IDH1-R132H mutation and ATRX status and showed that the IDH1-R132H and (or) ATRX status could be necessary to provide the basic molecular information for the “integrated diagnosis” of gliomas." (PMID 26918938, 2016). "Our results showed that the IDH1-R132H and (or) ATRX loss status could be necessary to provide the basic molecular information for the “integrated diagnosis” of gliomas." (PMID 26918938, 2016). "Our results revealed that IDH1-R132H dominated in grade II/III gliomas and secondary GBM." (PMID 26918938, 2016). "The IDH1-R132H inhibitor AGI-5198 is active against glioma cells in vitro." (PMID 27023522, 2016). "Hypermethylation of CPEB1 was observed in gliomas containing a mutant IDH1 gene." (PMID 27256982, 2016). "In glioma patients, there is a possibility that a small number of molecular features such as CpG island methylation phenotype (G-CIMP) or IDH1 mutation status could be useful for prediction of the outcome." (PMID 26861698, 2016). "Furthermore, evidence for differential responsiveness to genotoxic therapy of IDH1 mutant versus IDH1 wild-type low-grade gliomas has been provided." (PMID 26858939, 2016). "Two of 10 grade IV gliomas who were examined the sequence of the IDH1 gene revealed IDH1 mutation and eight of 10 did not reveal IDH1 mutation." (PMID 27456199, 2016). "LDHA expression is silenced by hypermethylation in patient-derived mutant IDH1 glioma models." (PMID 27144334, 2016). "Importantly, several previous studies have shown that the expression of BCAT1 is necessary for the progression of IDH1 WT gliomas, which sustain an aggressive growth phenotype, and our data are in line with previous reports." (PMID 27626306, 2016). "It is important to note that IDH1 mutant gliomas demonstrate improved overall survival compared to their wild‐type counterparts, which may well be in some part due to their apparent inability to modify their mitochondrial metabolism in response to hypoxia." (PMID 27196610, 2016). "In further PLS-DA analysis using those 6 significant metabolites, glioma patients could be successfully classified by IDH-1 status with 94.4% of accuracy." (PMID 26967252, 2016). "Reduced MCT1 and MCT4 expression in mutant IDH1 gliomas could also have important implications for chemotherapy." (PMID 27144334, 2016).
glioma (continued). "Additional analysis of glioma–CpG island methylator phenotype (G–CIMP) positive and G–CIMP negative tumors has shown that DNA methylation patterns strongly correspond to the status of IDH1 mutation." (PMID 27172220, 2016). "Although the genetic and epigenetic landscapes of IDH1 mutation gliomas have been extensively studied, whether IDH2 mutation gliomas have unique genetic and epigenetic characteristics that can be used as targets for future intervention is unknown." (PMID 27245697, 2016). "Identification of IDH1-R132H and ATRX loss status in the primary-recurrent gliomas may aid in treatment strategy selection, therapeutic trial design, and clinical prognosis evaluation." (PMID 26918938, 2016). "In summary, our finding that the expression of MCT1 and MCT4 is reduced in mutant IDH1 gliomas highlights the unusual metabolic reprogramming that occurs in mutant IDH1 tumors and has important implications for our understanding of these tumors and their treatment." (PMID 27144334, 2016). "IDH1/2 mutations identified thus far are heterozygous and produce single amino acid substitutions either at arginine 132 (R132) in IDH1 or arginine 172 (R172) in IDH2 in glioma and leukemia, or at arginine 140 (R140) in IDH2 in AML." (PMID 27548812, 2016). "AGI‐5198, an IDH1 inhibitor, was tested in a heterozygous IDH1 mutant glioma cell line (TS603)." (PMID 25864878, 2015). "Approximately 70% of IDH1 mutations were found in grade II and III gliomas and secondary GBMs." (PMID 26115094, 2015). "Indeed the results of the present study are consistent with previous studies which found that the vast majority of patients diagnosed with IDH1-positive gliomas are younger than 50 years old." (PMID 25849605, 2015). "Positive IDH1 staining was observed in 38 (34.86%) cases of glioma." (PMID 27275230, 2015). "The DNA methyltransferase inhibitors 5-azacytidine and decitabine are of particular interest, where 5-azacytidine has been shown to reduce the proliferative index in an in vivo IDH1 glioma model and decitabine repressed the migration capacities of Sdhb−/− cells." (PMID 26472283, 2015). "Our study evaluated the influence of IDH1/2 mutation, 1p/19q codeletion, TERTp mutation and EGFR amplification in the prognostic value of histological grade in a cohort of 214 cases of lower-grade gliomas." (PMID 26369702, 2015). "Mutations in IDH1 and IDH2 are found in gliomas and in acute myeloid leukemia." (PMID 26231040, 2015). "In this study, we aim to examine a panel of molecular markers including IDH1/2 mutation, 1p/19q codeletion, TERTp mutation and EGFR amplification as to their impact on the prognostic value of histological grade in a cohort of lower-grade gliomas." (PMID 26369702, 2015). "Therefore, it is possible that TGF-β signaling is enriched in the IDH1/2 population but is also present in other subgroups of glioma." (PMID 25529192, 2015). "Using AGI-5198, Rohle and colleagues demonstrated that mutant IDH1 inhibition blocked production of D-2HG by the mutant enzyme in a dose-dependent manner, and inhibited tumor growth in mouse xenografts and promoted cell differentiation in glioma cells." (PMID 26368816, 2015). "IDH1/2 combined with Ki-67 was used to re-classify glioma patients into five groups." (PMID 26338964, 2015). "Notably, low Ki-67 expression did not necessarily predict better prognosis than moderate Ki-67 expression among the IDH1/2 mut gliomas." (PMID 26338964, 2015). "For highly mutated cancer sites such as colon or stomach, our results confirm a strong association between BRAF mutation and COAD-CIMP but do not show any particular associations with IDH1/2, which have been reported to be causal in gliomas and leukemia." (PMID 26463173, 2015). "Mutations in IDH genes (IDH1 and IDH2) are observed in over 70% of low-grade gliomas and some GBM." (PMID 26485760, 2015).